STAT3 (signal transducer and activator of transcription 3)
Diseases named in the same sentence as STAT3 in open-access papers (continued):
Sharing a sentence is not in itself a finding about the gene and the disease.
tumor (continued). "STAT3 regulates basic biological processes essential to tumorigenesis, including cell-cycle progression, apoptosis, tumor angiogenesis, invasion and metastasis, and tumor-cell evasion of the immune system." (PMID 37298367, 2023). "STAT3 has also been reported to induce the expression of HIF-1α and cause tumor angiogenesis." (PMID 37239383, 2023). "Importantly, re-expression of OPN rescued defective Stat3 phosphorylation, tumor cell proliferation as measured by colony formation assay, as well as tumor cell migration in wound healing assays." (PMID 36813768, 2023). "The activation of Stat3 promoted cell division and reduced cell apoptosis, and the inhibition of p-Stat3 inhibited tumor growth by inducing tumor cell apoptosis, increasing dendritic cell activation, reducing tumor Treg and CD8+ T-cell activation, and decreasing the accumulation of MDSCs." (PMID 37375842, 2023). "For example, it has been observed that dioscin induced macrophage M2-to-M1 phenotype transition in vitro and inhibited IL-10 secretion, and it may act as a new anti-tumor agent by down-regulating STAT3 and JNK signaling pathways in macrophages in vitro." (PMID 37816138, 2023). "In addition, a TUNEL assay showed that astaxanthin and si-STAT3 both increased the number of apoptotic cells in tumor tissues." (PMID 38031104, 2023). "The role of STAT3 overexpression in tumor tissue remains inconclusive." (PMID 37371647, 2023). "Afatinib enhances PD-L1 expression in tumor cells through the STAT3/PD-L1 pathway." (PMID 37324014, 2023). "As evidenced by experimental results, the STAT3/VEGFR2 axis can promote tumor development." (PMID 37329188, 2023). "S1PR1 and STAT3 stimulate and activate each other to synergistically enhance tumor growth." (PMID 36714534, 2023). "Furthermore, STAT3 regulates the synthesis of IL-6, and IL-6 is also released by the immune cells in the tumor microenvironment." (PMID 37176160, 2023). "Moreover, factors in TME such as GM-CSF, G-CSF, SCF or S100A8/9 released from tumor cells can recruit MDSCs for proliferation via STAT3 and c/EPBβ." (PMID 37217620, 2023). "First, as noted, many of the cytokines that may be activating STAT3 in the tumor microenvironment are also activating STAT1." (PMID 38022653, 2023). "The transcriptional regulator STAT3 is also critical in vertebrate development and mature tissue function, including the control of inflammation and immunity, and plays a central role in regulating the anti-tumor immune response." (PMID 37998829, 2023). "In addition, IL-6/JAK/STAT3 signaling has been demonstrated to play important roles in tumor progression and aggressiveness in several cancers." (PMID 37488213, 2023). "They argued that high expression of PLCG2 might help form anti-tumor TME via IL-6/JAK/STAT3 signaling pathway, and then promote the proliferation, invasion and metastasis of tumor cells." (PMID 37074454, 2023). "IL6 and other observed pro-inflammatory cytokines as well as the proangiogenic factor VEGF are involved in STAT3-regulated pathways and thus might contribute to tumor growth induction." (PMID 35841421, 2023). "During tumor progression, inflammation triggers cancer cell stemness via STAT3 dependent pathways." (PMID 36845555, 2023). "Furthermore, we performed in vivo assays in BALB/c nude mice and in vitro assays to show that STK24-regulated tumor angiogenesis depends on STAT3." (PMID 36720310, 2023). "The abnormal activation of STAT3 renders the tumor microenvironment of GBM immunosuppression." (PMID 36923251, 2023). "AMPK inhibits tumor proliferation by suppressing STAT3 activation." (PMID 36911202, 2023). "In addition, IFN-α treatment of patients with cutaneous melanoma significantly modulates the balance of STAT1/STAT3 in tumor cells and host lymphocytes." (PMID 37047709, 2023).
tumor (continued). "CO-IP and post-mass spectrometry bioinformatics analyses revealed that TROAP may combine with signal transducer and activator of transcription 3 (STAT3) to achieve tumor progression in KIRC; this was verified by functional recovery experiments." (PMID 37298609, 2023). "Concurrently, tumor-secreted chemokines recruit resident microglia in the brain, which undergo a transformation into a macrophage-like immune phenotype upon activation of multiple signaling pathways, including STAT3, NF-κB, mTOR, PI3K/Akt, and Wnt/β-catenin." (PMID 37700840, 2023). "In addition, through literature search, we have found few studies on pan-cancer analysis of STAT3 from the perspective of overall tumor microenvironment." (PMID 37724127, 2023). "STAT3 is an important regulator in the metabolism of tumor cells." (PMID 36865551, 2023). "This substance interferes with the phosphorylation of STAT3 by Janus family kinases (JAKs), SRC tyrosine kinases and ABL tyrosine kinases in tumor cells, inhibiting the formation of STAT3 dimer nuclear signals in tumor cells and thus suppressing the tumor itself." (PMID 38104104, 2023). "Similarly, inhibition of STAT3 by Stattic evidently abrogated the tumor growth induced by active ARF6 overexpression in Huh7 cells." (PMID 37716993, 2023). "Moreover, due to some limitations of oligonucleotide-based therapeutics, the importance of carriers that can deliver nucleic acid molecules to affect the STAT3 in cancer cells and cells of the tumor microenvironment (TME) was pointed out." (PMID 38067351, 2023). "STAT3-degrader SD-36 can effectively degrade STAT3 in tumor cells." (PMID 37526084, 2023). "Emodin inhibited human HCC orthotopic tumor growth and STAT3 activation in athymic male nu/nu mice." (PMID 38203502, 2023). "Tregs suppress the immune system’s anti-tumor response in a STAT3- and STAT5-mediated fashion." (PMID 37173951, 2023). "As data from clinical trials of pyrimethamine become available, it will be important to determine whether the therapeutic activity of this drug correlates with the magnitude of transcriptional activation of STAT3 in tumor cells." (PMID 34953855, 2022). "In addition, the co-injection of TANs, TAMs, and STAT3-knockout iCCA cells in xenograft experiments reduced metastasis, suggesting that STAT3 mediates the tumor-promoting effects of these cytokines in iCCA cell lines." (PMID 36077744, 2022). "Results showed that H182 treatment suppressed Stat3 DNA-binding activity in tumor tissues (treated T vs. untreated control), in parallel with the suppression of the expression of Stat3 downstream genes, including c-Myc, VEGF, and survivin, compared to untreated control tumors." (PMID 35276290, 2022). "The activation of STAT3 could be observed in various tumors, which was closely related to inflammation and immunity and promoted tumor progression as an oncogene." (PMID 35707465, 2022). "Furthermore, JAK2/STAT3 signaling pathway also serve as a crucial mediator for the anti-tumor effects of Scoparone, β-citric acid and Atractylenolide II." (PMID 35818076, 2022). "In addition to sustaining tumor cells growth and assisting their metastatic ability, IL-6 was also reported to reduce cisplatin-triggered apoptosis in breast cancer cells via the STAT3 pathway." (PMID 36324128, 2022). "However, NF-κB is also involved in anti-tumor immune responses, and in contrast, STAT3 restrains the NF-κB-mediated anti-tumor immunity." (PMID 36499154, 2022). "Patients with high STAT3 expression have a worse tumor stage and prognosis." (PMID 36118847, 2022). "Thus, lentivirus-mediated overexpression of STAT3 partially reversed the anti-tumor effect of Stattic via STAT3 reactivation." (PMID 35288541, 2022). "The STAT3/C-myc pathway is closely related to tumor immune response." (PMID 36420358, 2022).
tumor (continued). "High STAT3 expression may contribute to the early stages of tumor formation and development by inhibiting apoptosis of tumor cells." (PMID 35356799, 2022). "In ESCC, the overexpression of miR-874 can inhibit tumor development by targeting STAT3." (PMID 35465322, 2022). "Studies have shown that dysregulated IL-6 or JAK2 can reprogram the STAT3 pathway in metastatic tumor cells, induce recruitment of myeloid-derived suppressor cells (MDSCs) and polarized macrophages, and repress the infiltration of CD8+ T cells to evade host immunity in NSCLC." (PMID 36559280, 2022). "These macrophages are known as tumor-supportive macrophages (M2) and express STAT3." (PMID 35448036, 2022). "In these signaling pathways, STAT3 is considered to be a key signaling molecule of the IL-6-gp130 pathway because it acts as an oncogenic driver and plays an important role in mediating tumor-promoting inflammation." (PMID 36010693, 2022). "Topical iontophoretic administration of a curcumin and anti-STAT3 siRNA nanosystem demonstrated similar tumor inhibition efficacy as observed for i.t. injection, but significantly higher compared to liposomes of each of the compounds individually by either route." (PMID 36145569, 2022). "Disruption of the IL-6/IL-6R/STAT-3 axis using Stt and Tcz may be a therapeutic target in PCa based on the molecular characteristics of the tumor cells." (PMID 35703345, 2022). "Overall, these data provide evidence that STAT3 suppresses the anti-tumor activity of NK cells." (PMID 35865518, 2022). "Moreover, inhibition of G3BP1 decreased the STAT3 activation and, as a result, alleviated tumor growth and metastasis were observed not only in vitro but also in orthotopic xenografts." (PMID 36230984, 2022). "Mechanistically, the disturbed cytokine receptor by reducing activity of PPTLS-APE1/Ref-1 inhibited inflammatory signaling leading to the inactivation of the p21-activated kinase 1-mediated signal transducer and activator of transcription 3/nuclear factor-κB axis in tumor tissues." (PMID 36012284, 2022). "It has been reported that miRNAs could inhibit tumor progression by targeting STAT3 in different tumors." (PMID 36295083, 2022). "A master inducer of STAT3 activation in tumor and inflammatory cells is IL-6." (PMID 35993361, 2022). "Here, we summarize the current knowledge on how STAT3 contributes to NK-cell fitness and tumor cell evasion from NK cells, and speculate on how targeting STAT3 may affect NK-cell tumor surveillance." (PMID 35865518, 2022). "Similarly, tumor tissue samples with high positivity for tumor cell nuclear STAT3 exhibited high cytoplasmic STAT3 levels and tumors with positivity for nuclear STAT1 showed increased nuclear STAT3." (PMID 35267462, 2022). "Despite the importance of STAT3 to mediate muscle wasting and the emerging anti-atrophy protective effect of RT during cancer, the effect of RT on STAT3-mediated muscle atrophy in tumor-bearing mice is unknown." (PMID 35847939, 2022). "Tumor-mediated activation of STAT3 in CD163+ TAMs resulted in pro-tumor TAM polarization." (PMID 36686729, 2022). "Treatment successfully inhibited tumor growth mediated by down-regulation of STAT3 and p-NFkB p65." (PMID 36144329, 2022). "In addition, AKR1C1 can directly interact with and promote phosphorylation of STAT3, enhancing the binding of STAT3 to the promoter regions of target genes, and then transactivating these genes, promoting tumor metastasis." (PMID 36263088, 2022). "Additionally, shAPE1‐loaded RCSC‐EVs suppressed the Erlotinib resistance of NSCLC via the IL‐6/STAT3 axis both in vitro and in vivo, as reflected by impeded malignant phenotypes and xenograft tumour formation." (PMID 35605028, 2022). "The knockdown of STAT3 or SRF significantly suppresses tumor invasive properties." (PMID 35538578, 2022).
tumor (continued). "In addition to tumor cells, PD‐L1 is also overexpressed via the STAT3 pathway on the surface of neutrophils with the engagement of PD‐1 to block the activation of T‐cells and NK cells." (PMID 35356799, 2022). "Thus, apart from angiogenesis, VEGF is also responsible for CSCs’ self-renewal and tumor-initiating via the VEGFR-2/STAT3 signaling." (PMID 36359888, 2022). "Constitutive Stat3 activation early in head and neck carcinogenesis could enhance tumor progression by blocking tumor cell apoptosis." (PMID 34875483, 2022). "STAT3 is persistently activated in tumor-infiltrating B cells during tumor growth." (PMID 35759090, 2022). "Increasing evidence suggests that STAT3 is involved in regulating tumor cell immune evasion." (PMID 36557902, 2022). "STAT3 is a transcription factor that is involved in tumor cell proliferation and metastasis." (PMID 35211240, 2022). "In addition, we showed that STAT3 participates in OCLN‐mediated regulation of tumour angiogenesis in BLCA." (PMID 35224833, 2022). "A single administration of the degrader 114 (SD-91) could selectively and continuously reduce STAT3 in tumor tissues." (PMID 35680848, 2022). "STAT3 inhibition experiments show immune cell specific effects, as demonstrated in the Mx1-cre-mediated STAT3 deletion model, in which antigen presentation by dendritic cells was enhanced to promote anti-tumor T cell responses." (PMID 35053592, 2022). "In human NSCLC, metformin targets STAT3, curbing tumor proliferation." (PMID 36672573, 2022). "In addition to STAT3 overexpression in tumor tissues, cells bearing the activated STAT3 were transformed to form tumors in nude mice." (PMID 35356799, 2022). "Dysregulated STAT3 activates immunosuppressive tumor-infiltrating myeloid-derived suppressor cells (MDSCs), TAMs, and T regulatory cells; STAT3 further induces expression of upstream cytokines and growth factors creating a vicious autocrine and paracrine positive feedback loop." (PMID 35371975, 2022). "Similarly, docetaxel exerts its anti-tumor activity by selective depletion of Tregs and reduction of MDSCs at the tumor site via activation of STAT3 signaling." (PMID 36003765, 2022). "HAR1A functions as a tumor suppressor in NSCLC by regulating the STAT3 signaling pathway." (PMID 35740511, 2022). "Therefore, inhibitors of IL-6/STAT3 signaling pathway are presently in clinical and/or preclinical development to inhibit tumor growth and relieve immunosuppression." (PMID 34976184, 2022). "STAT3 plays a crucial role in mediating oncogenic transformation and inducing tumor formation." (PMID 35744840, 2022). "In addition, STAT3 activation by IL-6 and IL-8 produced by tumor cells has been reported to decrease levels of NKG2D and NKp30 on NK cells." (PMID 35865518, 2022). "Furthermore, in adaptive immune subsets, increased Stat3 activity inhibits the accumulation of effector T cells by which inhibit their anti-tumor effects." (PMID 36454780, 2022). "Additional mouse strains, e.g., with a constitutive STAT3 activation in Col1+ fibroblasts on a HIF1 deficient background, could be helpful for determining the contribution of HIF-dependent tumor progression in more detail in our setup." (PMID 35326623, 2022). "This allows speculation that up-regulation of STAT3 and activation of the NF-κB pathway in malignant cells may result in the significant up-regulation of tumor invasiveness and, thus, tumor progression." (PMID 36551618, 2022). "Its role is related to the stage of tumor development and the location of STAT3 protein." (PMID 35432564, 2022). "In addition, activation of the CXCL1/CXCR2 signaling axis was also observed to promote tumor angiogenesis and progressive growth by activating STAT3 and enhancing VEGF levels." (PMID 36612163, 2022).
tumor (continued). "The significant role of STAT3 pathway in tumor progression is also involving, which may provide a new idea for the treatment of HCC." (PMID 35033067, 2022). "Solamargine at low doses regulates the biological function of immune cells by inhibiting the LIF/Stat3 signaling pathway, reshaping the tumor microenvironment, and inhibiting the process of tumor cell heterogeneity, thereby exerting a synergistic antitumor effect." (PMID 36052142, 2022). "Osteoclast-secreted IL-19 activates JAK1/STAT3 signaling in IL20RB-expressing tumor cells." (PMID 36006737, 2022). "Therefore, STAT3 inhibitors are expected to yield better results in combination with immunotherapies by improving the tumour immune microenvironment." (PMID 35665592, 2022). "At the same time, these tumor-derived factors may serve as STAT3 activators in the tumor milieu, enhancing STAT3 signaling in various immune cell subsets and tumor-associated fibroblasts." (PMID 36551618, 2022). "Activation of this IL-6/STAT3 axis-guided fructose metabolism promotes tumor cell growth." (PMID 35813468, 2022). "STAT3 cooperates with other targets in promoting glycolysis or lipid catabolism, which have potential roles in different aspects of the metabolism switches in cancer cells that support tumor progression." (PMID 36438791, 2022). "Moreover, activated STAT3 motivates the secretion of many chemokines and cytokines such as, IL-6 and IL-16 to maintain activation of immune cells in the tumor tissue." (PMID 36374927, 2022). "Notably, several studies have shown that matrix metalloproteinases (MMPs) such as MMP2 and MMP9 contribute to tumor angiogenesis, which can be suppressed by inhibiting STAT3 activity." (PMID 36557902, 2022). "Similarly, the down-regulation of p-JAK2 and p-STAT3 in the tumor tissues of the mice co-treated with β-Ele and cisplatin were confirmed by IHC assay and H-score." (PMID 35909161, 2022). "The complex I catalyzes the electron transfer from NADH to ubiquinone in the first step of the mitochondrial respiratory chain, and its subunit NDUFA13, in addition to be required for electron transfer, functions as a tumor suppressor that binds to STAT3 and inhibits its transcriptional activity." (PMID 35359604, 2022). "Here, we investigated whether IL-6-induced STAT3 activation can reverse the anti-tumor effect of Stattic in PCCs." (PMID 35288541, 2022). "IL‐6‐mediated STAT3 activation is common in the tumor microenvironment." (PMID 37829248, 2022). "In addition, CAFs produce more IL-6 than fibroblasts in normal tissues preventing tumor cell apoptosis through a STAT3-dependent mechanism and enhancing angiogenesis." (PMID 36419156, 2022). "In summary, our study suggests that Niraparib interferes with SRC/STAT3 pathway to increase apoptosis of tumor cells with or without BRCA mutations." (PMID 36324587, 2022). "Moreover, the phosphorylation of p38-MAPK/AKT/STAT3 was enhanced by IL-22 in the tumor samples, and these results were similar to those in vitro." (PMID 35669104, 2022). "mc-1Stat3-treated tumor-bearing mice show a significantly prolonged inhibition effect of tumor growth after treatment arrest from days 21–26, whereas, in the same time period, rapid tumor growth occurred with dc-Stat3." (PMID 35847174, 2022). "Furthermore, some tumor-promoting neutrophils released lipocalin 2 (LCN2) protein activated by STAT3 to induce tumor metastatic growth." (PMID 35719975, 2022). "MiR-1246 targets telomeric repeat binding factor 2 interacting protein (TERF2IP) and markedly promotes M2 macrophage polarization by activating the STAT3 pathway and inhibiting the NF-κB pathway, and ultimately leading to tumor proliferation, migration and invasion." (PMID 36071472, 2022). "DIM treatment could not affect the miR-21 level and protein levels of PTEN, PIAS3 and p-STAT3 in the splenic MDSCs from miR-21−/− tumor-bearing mice." (PMID 35773674, 2022).